TLR4 (toll like receptor 4)
Diseases named in the same sentence as TLR4 in open-access papers (continued):
Sharing a sentence is not in itself a finding about the gene and the disease.
psoriasis (64 papers, 2014 to 2025). An autoimmune condition characterized by red, well-delineated plaques with silvery scales that are usually on the extensor surfaces and scalp. "It has been shown that targeting and inhibiting TLR4 effectively prevents the incidence of auto-inflammatory symptoms in a mouse model of IL-36 receptor antagonist deficiency-induced psoriasis." (PMID 40343294, 2025). "Polymorphisms within the TLR4 gene have been associated with a number of immune-mediated inflammatory diseases, such as psoriasis." (PMID 36382932, 2022). "The sample size was not sufficient for statistical measurements to verify significant relationship between the SNPs in PSORS1C3, CARD14 and TLR4 genes and psoriasis susceptibility in the Vietnamese population." (PMID 36382932, 2022). "Investigations on the effects of PSORS1C3, CARD14, and TLR4 polymorphisms are gradually increasing in the field of biomarker study in inflammatory diseases, such as psoriasis." (PMID 36382932, 2022). "Our study aimed to assess the relationship among PSORS1C3, CARD14 and TLR4 polymorphisms, inflammatory expression and psoriasis susceptibility." (PMID 36382932, 2022). "TLR4 expression is upregulated in PBMCs in human patients with psoriasis, and variants of TLR4 are implicated in both plaque-type psoriasis and psoriatic arthritis." (PMID 31105556, 2019). "Significant association was observed between a missense variant rs4986790 of TLR4 (Asp229Gly) and plaque type psoriasis (p = 2 × 10−4) which was also notable in those with psoriatic arthritis (p = 2 × 10−4) and early-onset psoriasis (p = 8 × 10−4)." (PMID 26830904, 2016). "Nonetheless, it is of significant interest that a functional missense variant in TLR4, known to be associated with conditions genetically linked to psoriasis, shows significant association with psoriasis and psoriatic arthritis in this study." (PMID 26830904, 2016). "In this work, we predict that IL-6-mediated inflammation in psoriasis could be involved in variant TLR4 genotypes." (PMID 36382932, 2022). "In conclusion, the PSORS1C3, CARD14 and TLR4 polymorphisms and haplotypes may be correlated with risk of suffering psoriasis and the IL-6-mediated chronic inflammation in psoriasis could be partially regulated by the TLR4 functional variant." (PMID 36382932, 2022). "Additionally, we have previously reported an association between TLR4 loci (rs10759932; rs7044464; rs752998) and early-onset psoriasis (age of onset <40 years) in 664 patients and 566 healthy population based controls." (PMID 26830904, 2016). "Therefore, due to the increasing evidence suggestive of a role for TLR4 in the pathogenesis of psoriasis, we investigated polymorphisms across the gene with a high-density SNP panel in a cohort of 2826 UK patients with chronic plaque type psoriasis." (PMID 26830904, 2016). "Besides, several SNPs in TLR4 gene have been reported associated with psoriasis susceptibility, we additionally indicated that the AT genotype of the SNP rs1018673641 in TLR4 gene could be the high-risk genotype for psoriasis." (PMID 36382932, 2022). "Moreover, TLR4 polymorphisms have been associated with different autoimmune conditions, including chronic plaque psoriasis and psoriatic arthritis, suggesting a key role of this receptor in inflammatory pathways associated with psoriasis." (PMID 35571214, 2022). "Therefore, it may be suggested that NETs may be important factors in the development of psoriasis, especially since LPS, which, like imiquimod, is a TLR4 agonist which causes a strong activation of NETosis." (PMID 32947961, 2020). "Among them, it has been observed that, in vitro and using a common mouse model of psoriasis-like inflammation, Toll-like Receptor 4 (TLR4) signaling and the activation of IL-36 by neutrophils are able to enhance skin inflammation through NETs release." (PMID 40283181, 2025). "Self-ligand-induced TLR4 activation in psoriasis promotes keratinocyte proliferation and the chronic inflammatory loop." (PMID 41002387, 2025).
psoriasis (continued). "TLR2 and TLR4 expressions are heightened in peripheral blood mononuclear cells and keratinocytes of psoriasis patients." (PMID 39859462, 2025). "Based on the obtained results, it can be concluded that IVM-gel can effectively reduce psoriasis lesions due to its therapeutic properties, such as anti-inflammatory effects via targeting TLR4/p65 NF-κB." (PMID 40343294, 2025). "In the inflammatory lesion psoriasis, NETs can activate the Toll-like receptor 4 (TLR4) signaling pathway to amplify skin inflammation, and further recruiting neutrophils to the skin, thus exacerbating skin inflammatory injury." (PMID 41208960, 2025). "By focusing on the activation profile of platelets and their interaction with immune cells, we identify cell-surface proteins CD32+CD154+ and TLR2+TLR4+, distinguishing unique platelet subsets in psoriasis patients." (PMID 41350257, 2025). "No appreciable evidence was found on HaCaT hyperproliferation, as often reported in the literature, but we showed substantial differences between specific genes involved in the inflammation pattern related to psoriasis such as TLR-4, IL-6 and IL-23." (PMID 39941078, 2025). "Psoriasis inhibits TLR4 function on dendritic cells, leading to dendritic cell dysfunction, release of anti-inflammatory cytokines, and suppression of hypersensitivity reactions and inflammation." (PMID 40343294, 2025). "The findings suggest that PLE hampers psoriasis progression by hindering the activation of the TLR4/NF-κB signaling pathway." (PMID 40333872, 2025). "Overall, the advantages of this study include the utilization of a well-established imiquimod-induced psoriasis model and a thorough investigation of the mechanism of silymarin action via the NF-κB/TLR4 signaling pathway." (PMID 41170194, 2025). "Psoriasis inhibits the function of TLR4 on dendritic cells, leading to their dysfunction, reduced secretion of anti-inflammatory cytokines, and a decrease in hypersensitivity reactions and inflammation." (PMID 41170194, 2025). "Fluorescence immunostaining results indicated that IMQ significantly increased TLR4 and p65 NF-κB protein expression in psoriasis model mice." (PMID 40343294, 2025). "The role of TLR4 in defense against microbes on the skin surface and in the pathogenesis, occurrence, and progression of psoriasis has been demonstrated in several studies." (PMID 40343294, 2025). "Network pharmacology analysis showed that 20 transdermal constituents were associated with potential therapeutic targets for psoriasis, including TNF, MMP9, TLR4, ICAM1, EGFR, and MAPK14." (PMID 41012530, 2025). "This research involved determining PASI (Psoriasis Area Severity Index), spleen-to-body weight index, TLR4 and NF-κB expression using immunohistochemistry, and histopathological evaluation on mice." (PMID 40343294, 2025). "Regarding the pathogenesis of psoriasis, some scholars believe that it is related to the TLR4/NF-κB signaling pathway, while some scholars believe that the pathogenesis of psoriasis is related to the PI3K/Akt signaling pathway." (PMID 40333872, 2025). "The serum levels of HMGB1, TLR4, IL‐23, and IL‐17A in psoriasis patients were significantly higher than healthy controls, especially in severe patients, and positively correlated with the severity index." (PMID 38414294, 2024). "HMGB1, TLR4, IL‐23, and IL‐17A serum concentrations in psoriasis patients were significantly elevated compared with those in healthy controls (t = 7.716, 2.433, 4.443, and 10.339, respectively, all p < .05 or .01)." (PMID 38414294, 2024). "Significant in the development of psoriasis and AD, Flii proteins hinder MyD88 binding to TLR4, which thus inhibits the TLR4-NF-κB pathway and cellular autophagy." (PMID 38606161, 2024). "Serum concentration of HMGB1, TLR4, IL‐23, and IL‐17A were all positively correlated with psoriasis patients' PASI (r = 0.66, 0.68, 0.65, and 0.65, respectively, all p < .001)." (PMID 38414294, 2024).
psoriasis (continued). "Second, although HMGB1 has the potential to promote Th17 cell differentiation and induce IL‐17 expression in PBMCs of psoriasis patients by IL‐23 and TLR4 signaling pathways, more detailed mechanisms need to be explored and explained." (PMID 38414294, 2024). "Solenopsin analogs, which have shown success in mouse models of psoriasis, also downregulate TLR4 expression." (PMID 38067173, 2023). "Previous studies have also reported an association between HERVs and psoriasis, and the members of the HERV-W family have been found to activate the immune system via CD14/TLR4 signalling and promote the development of a Th1 type of immune response." (PMID 38069048, 2023). "Meanwhile, this was the case for 16 of the itch-associated genes in MCs isolated from psoriasis skin, including CTSB, TLR4, and TACR1 (training set AUC OOB = 1, OOB Error rate = 11.11%, validation set AUC = 0.875, 95% CI = 0.63–1)." (PMID 37681909, 2023). "The proinflammatory activity of NETs and LCN2 induction in psoriasis was suggested to be dependent on TLR4/IL-36R crosstalk and MyD88/nuclear factor-kappa B (NF-kB) downstream signaling." (PMID 37746070, 2023). "In mouse models, TLR4 both helps to initiate the development of psoriasis plaques and to maintain the presence of these lesions." (PMID 38067173, 2023). "TLR4 hyperstimulation induces the uncontrolled inflammatory process that is observed in many illnesses, including neurodegenerative, autoimmune and psoriasis)." (PMID 36568291, 2022). "A recent study indicates that psoriasis-like inflammation damages the renal function via the TLR4-mediated IL-6 production in mice." (PMID 36382932, 2022). "This study showed the increased risk of developing psoriasis in patients carrying SNPs in PSORS1C3, CARD14 and TLR4 genes." (PMID 36382932, 2022). "Role of TLR4 signaling is also of special importance in regulating psoriasis-like inflammation in patients with kidney failure." (PMID 36382932, 2022). "The release of cytokines, such as IL-1β and TNF-α/IL-23/IL-17 by TLR4-mediated inflammatory immune cells is related to the severity of psoriasis." (PMID 36382932, 2022). "A recent study reveals that in patients with psoriasis, activation of the NF-κB signaling is triggered by TLR4 to exert chronic inflammatory condition." (PMID 36382932, 2022). "Similar to CARD14 gene, the role of TLR4 gene is related to the development of a number of inflammatory diseases, such as psoriasis." (PMID 36382932, 2022). "In this study, SNP profiling of PSORS1C3, CARD14, and TLR4 genes in 71 patients with psoriasis and 46 healthy individuals by direct DNA sequencing was investigated to determine disease-associated SNPs." (PMID 36382932, 2022). "The expression of Toll-like receptor 2(TLR2) and TLR4 in the outer keratinocytes and peripheral blood mononuclear cells of patients with psoriasis is increased." (PMID 34215260, 2021). "TRIF is an adaptor in the signal transduction cascade triggered by toll-like receptors (TLRs), and our previous study also found that TLR4 is elevated in the psoriasis mouse model." (PMID 32075957, 2020). "Although toll-like receptor 4 (TRL4) mediates the immune response in psoriasis, the regulatory role of TLR4 in keratinocyte proliferation in psoriasis has been identified as a direct target of downregulated miR-181b." (PMID 32806619, 2020). "The expression of TLR2 and TLR4 on peripheral blood mononuclear cells and keratinocytes is elevated in patients with psoriasis." (PMID 31815151, 2019). "In summary, these data suggest that LCN2, secreted by activated keratinocytes and neutrophils, is a critical inflammatory factor down-stream of TLR4/IL-36R that participates in and sustains NETs-exacerbated psoriasis inflammation." (PMID 31024570, 2019). "They showed that the percentages of TLR-2+ and TLR-4+ lymphocytes are higher in patients with psoriasis than in the general population." (PMID 31554206, 2019).
psoriasis (continued). "In summary, these results outline the mechanisms for the proinflammatory activity of NETs in skin and identify NETs/TLR4 as novel therapeutic targets in psoriasis." (PMID 31024570, 2019). "The contribution of NETs to psoriasis pathogenesis has been unclear, but here we demonstrate that NETs drive inflammatory responses in skin through activation of epidermal TLR4/IL-36R crosstalk." (PMID 31024570, 2019). "Next, we explored the therapeutic potential of TLR4 inhibition for NETs-exacerbated psoriasis-like inflammation in the IMQ mouse model." (PMID 31024570, 2019). "S100A8 and S100A9 are antimicrobial peptides that form a heterodimer called calprotectin which interacts with Toll-like receptor 4 (TLR-4) and exacerbates psoriasis by activating complement factor C3 and recruiting neutrophils." (PMID 30279326, 2018). "Recent functional studies support this notion having suggested a role for TLR4 in the pathogenesis of psoriasis." (PMID 26830904, 2016). "Moreover, heat shock proteins (HSPs) such as HSP27, HSP60, HSP70, and HSP90 are overexpressed in psoriasis keratinocytes, acting as autoantigens that activate antigen-presenting cells via TLR4, promoting their maturation and the secretion of TNF-α and IL-12." (PMID 39859462, 2025). "In addition, TLR-4 expression increased on peripheral blood mononuclear cells of psoriasis patients compared to controls." (PMID 39941078, 2025). "Our findings suggest that PLE is effective in improving psoriasis-like symptoms, which might be ascribed to the inhibition of the TLR4/NF-κB and PI3K/AKT inflammation pathway." (PMID 40333872, 2025). "Evidence suggests that TLR4 is involved in the immune response in the psoriasis pathogenesis." (PMID 40343294, 2025). "In addition, there was also a positive correlation between every two detected indexes among HMGB1, TLR4, IL‐23, and IL‐17A in psoriasis patients." (PMID 38414294, 2024). "Regarding the fundamental role of the TLR4-NF-κB pathway in the pathogenesis of psoriasis, Flii may interfere with the binding of TLR4 to myeloid differentiation primary response protein 88 (MyD88), which thereby inhibits the NF-κB pathway." (PMID 38606161, 2024). "In the present study, we confirmed that both HMGB1 and TLR4 serum levels were positively correlated with IL‐23 in psoriasis and rHMGB1 can dose‐dependently increase its expression levels, further indicating the regulatory effect of HMGB1 on Th17 cell differentiation." (PMID 38414294, 2024). "Finally, suprabasin, an epithelial pro-inflammatory peptide, has also been indicated as possible regulator of mast cell activation via TLR4 leading to an increase in the inflammatory response, as demonstrated in psoriasis." (PMID 37834061, 2023). "Thus, the increased expression of TLR4 could indicate an altered susceptibility of MCs to endogenous ligands such as human beta-defensin 2, which has been shown to not only promote itch through TLR4 signalling in mice, but to be overexpressed in psoriasis skin." (PMID 37681909, 2023). "Unlike PSORS1C3 gene, reports on the effects of CARD14 and TLR4 haplotypes in psoriasis susceptibility are limited." (PMID 36382932, 2022). "Interestingly, we demonstrated that all the three haplotypes (A-G, GA-GA and G-T-T) in PSORS1C3 gene, the AG-CT-C haplotype in CARD14 gene and the T-T-T haplotype in TLR4 gene were detected at higher frequencies in patients with psoriasis compared to controls." (PMID 36382932, 2022). "These activated dendritic cells release inflammatory cytokines, such as TNF-α, IFN-γ, and interleukin-17 (IL-17), and in return, these cytokines promote keratinocyte proliferation and psoriasis progression with the involvement of the TLR4/NF-κB signaling pathway." (PMID 36233237, 2022). "Besides, further functional research is necessary for investigating the regulatory effects of the SNP rs1018673641 in TLR4 gene on inflammatory response in psoriasis." (PMID 36382932, 2022).
psoriasis (continued). "Thus miR-181b plays a crucial role in psoriasis via directly regulating the TLR4 expression and its function through Akt." (PMID 33510592, 2021). "In psoriasis, neutrophils infiltrate into the epidermis and secrete IL-17A, which induces basal keratinocytes proliferation, followed by the production of IL-23 and TLR4." (PMID 33253155, 2020). "These in vivo results demonstrate that the TLR4/MyD88/NF-κB-dependent signaling pathway is aberrantly activated in keratinocytes by NETs, and that targeting of this pathway can lead to improvement in psoriasis-like inflammation." (PMID 31024570, 2019). "Furthermore, daily topical treatment with the TLR4 inhibitor TAK-242 also reduced the severe psoriasis phenotype in IMQ mouse model." (PMID 31024570, 2019). "Furthermore, our data provide a rational basis for development of therapies specifically targeting the autoinflammatory loop of NETs-keratinocytes-IL-36 in psoriasis and identify TLR4 as novel therapeutic targets in psoriasis." (PMID 31024570, 2019). "Furthermore, a recent study has demonstrated an increase in TLR4 expression on peripheral blood mononuclear cells of psoriasis patients compared to controls." (PMID 26830904, 2016). "Indeed, upregulation of miR-339-5p or miR-489-3p may be associated with an anti-inflammatory phenotype, since these miRNAs have been associated with the inhibition of alcohol-induced brain inflammation or TLR4/NF-κB signaling in psoriasis, respectively." (PMID 37760011, 2023). "Furthermore, studies of TLR4 expression in healthy skin versus skin with atopic dermatitis, contact dermatitis, and psoriasis found that TLR4 became more expressed in the upper layers of skin with these conditions compared with healthy skin, where TLR4 was mainly in the basal layers." (PMID 38067173, 2023). "Therefore, genetic variation of TLR4 and CARD14 genes might be the contributing risk factors for psoriasis by modulating the cellular physiological processes." (PMID 36382932, 2022). "In conclusion, the deleterious effect of the SNP rs1018673641 in TLR4 gene could partially contribute to chronic inflammation in psoriasis and be a good candidate for further study on its role in regulating functional activation of immune cells in psoriatic patients." (PMID 36382932, 2022). "However, TLR4 expression increases in both forms of psoriasis." (PMID 33510592, 2021). "The roles of TLR2 or TLR4 in psoriasis still remain unclear." (PMID 31815151, 2019). "The scaffold function of IRAK4 plays a pivotal role not only in TLR4-mediated ALI, but also in TLR7/8-mediated psoriasis and TLR7/9-mediated SARS-CoV-2 infection." (PMID 40771916, 2025). "The research involved assessing the Psoriasis Area Severity Index (PASI), the spleen-to-body weight ratio, and the expression levels of TLR4 and NF-κB using immunohistochemical techniques in a mouse model." (PMID 41170194, 2025). "Recent studies have highlighted its involvement in promoting psoriasis development through various signaling pathways, such as the Th17, SREBP2-NLRC4, and TLR4/IL36R pathways." (PMID 40369189, 2025). "In psoriasis, the persistent activation of TLRs, particularly TLR2 and TLR4, along with sustained NF-κB signaling, drives chronic inflammation and promotes the differentiation and expansion of pathogenic Th1 and Th17 cells." (PMID 40558675, 2025). "Among them, HSP60, HSP70, and HSP90 are mainly involved in psoriasis and act through receptors such as TLR2, TLR4, and CD91." (PMID 38255845, 2024). "However, our present study provides further evidence that HMGB1 participates in the pathogenesis of psoriasis, which may exert its regulatory effect on Th17 cell differentiation and IL‐17A production by IL‐23 and TLR4 signaling pathways to amplify its inflammatory effects." (PMID 38414294, 2024). "For example, C/EBPδ has been shown to play a role in the pathogenesis of psoriasis and in acute inflammatory signaling by regulating COX-2, IL-6, and TLR4." (PMID 35543413, 2022).